UBE2E2 (ubiquitin conjugating enzyme E2 E2)
Description:
Accepts ubiquitin from the E1 complex and catalyzes its covalent attachment to other proteins. In vitro catalyzes 'Lys-11'- and 'Lys-48'-, as well as 'Lys-63'-linked polyubiquitination. Catalyzes the ISGylation of influenza A virus NS1 protein.
Synonyms: UBCH8; FLJ25157
Tractability: PROTAC: UniProt records ubiquitination sites on it; ubiquitination databases record sites on it.
Gene: Protein-coding gene on chromosome 3 (23,203,020 to 23,591,794, forward strand). Ensembl gene ENSG00000182247.
Subcellular location (Human Protein Atlas): Nucleoplasm
Pathways (Reactome):
Immune System: Antigen processing: Ubiquitination & Proteasome degradation
Gene Ontology:
Molecular function: ISG15 transferase activity; protein binding; ubiquitin conjugating enzyme activity; ubiquitin-protein transferase activity
Biological process: DNA damage response; ISG15-protein conjugation; positive regulation of G1/S transition of mitotic cell cycle; protein K11-linked ubiquitination; protein K48-linked ubiquitination; protein K63-linked ubiquitination; protein monoubiquitination; protein ubiquitination
Genetic constraint (gnomAD): Loss-of-function variants: 6 observed, 24.09 expected, observed/expected ratio (o/e) 0.25, 90% interval 0.14 to 0.49. The upper end of that interval is the gene's LOEUF score, 0.49, which puts it in group 2 of 6, group 1 being the genes least tolerant of losing a copy. Missense variants: 169 observed, 241.92 expected, observed/expected ratio (o/e) 0.7, 90% interval 0.62 to 0.79. Synonymous variants: 104 observed, 82.75 expected, observed/expected ratio (o/e) 1.26, 90% interval 1.07 to 1.48.
Homologues: Orthologues: chimpanzee UBE2E2 (100% identical), dog UBE2E2 (100% identical), macaque UBE2E2 (100% identical), pig UBE2E2 (100% identical), guinea pig UBE2E2 (99% identical), mouse Ube2e2 (99% identical), tropical clawed frog ube2e1 (96% identical), rat Ube2e2 (67% identical). Paralogues in human: UBE2E3 (88% identical), UBE2E1 (82% identical), UBE2D2 (47% identical), UBE2D4 (47% identical), UBE2D3 (46% identical), UBE2D1 (45% identical), UBE2Q2 (30% identical), UBE2Q1 (29% identical), UBE2L5 (26% identical), UBE2L6 (26% identical), UBE2L3 (25% identical), UBE2QL1 (17% identical).
Diseases named in the same sentence as UBE2E2 in open-access papers:
UBE2E2 is named in the same sentence as 17 diseases in open-access papers, as found by Europe PMC text mining. Sharing a sentence is not in itself a finding about the gene and the disease. The quoted sentences say what the papers report.
type 2 diabetes (13 papers, 2011 to 2025). "For BMI and psoriasis, among the 3 shared SNPs, rs13062101 was in proximity to UBE2E2, a gene linked to obesity and type 2 diabetes." (PMID 38550599, 2024). "UBE2E2, a gene associated with obesity and type 2 diabetes, encodes the ubiquitin-conjugating enzyme E2E2 expressed in adipose tissue, and it plays a regulatory role in insulin synthesis and secretion as well as adipocyte differentiation." (PMID 38550599, 2024). "Previous studies indicated the role of UBE2E2 and UBE2E2 gene polymorphisms in the pathogenesis of type 2 diabetes." (PMID 35207731, 2022). "All these loci, except UBE2E2, were also shown to be associated with type 2 diabetes in European populations." (PMID 23029454, 2012). "Japanese genome-wide association studies (GWAS) have identified the loci KCNQ1, UBE2E2, C2CD4A-C2CD4B, and ANK1 to be associated with type 2 diabetes." (PMID 23029454, 2012). "UBE2E2 (also called UbcH8) was first reported in 1997 and has been proposed to play a pathological role in various human diseases, including type 2 diabetes (T2D), rheumatic autoimmune disease, Parkinson’s disease, non-small cell lung cancer, hepatocellular adenoma and carcinoma." (PMID 36765041, 2023). "It is also reported that UBE2E2 is involved in adipocyte development and type 2 diabetes in humans." (PMID 33964893, 2021). "Three Japanese GWAS including ours, have identified the association of the potassium voltage-gated channel KQT-like subfamily member 1 (KCNQ1) locus, ubiquitin-conjugating enzyme E2E 2 (UBE2E2) locus and C2 calcium-dependent domain containing 4A (C2CD4A)-C2CD4B locus with type 2 diabetes." (PMID 22046406, 2011).
diabetes (4 papers, 2015 to 2022). "UBE2E2 (rs1496653) node is an ubiquitin-conjugating enzyme associated with diabetes in some reports, and with GDM in other studies." (PMID 36313769, 2022). "Previous studies indicated the association between UBE2E2 gene polymorphism and diabetes in various population." (PMID 35207731, 2022). "In light of sample ascertainment for diabetes in this cohort, a gene in 1 region, UBE2E2, was of interest because of prior associations with diabetes risk, however, stratification for diabetes provided highly concordant results with the unstratified analysis (data not shown)." (PMID 26569114, 2015).
Obesity (4 papers, 2022 to 2024). Accumulation of substantial excess body fat. "Other candidate genes which have been reported in humans, for example, the PMAIP1 and UBE2E2 genes are involved in human obesity." (PMID 37407918, 2023). "Collectively, these data suggest that UBE2E2 loss of function in mice results in modestly increased adiposity without overt obesity and without an obvious disruption of glucose homeostasis." (PMID 39656538, 2024). "Therefore, we subjected Ube2e2+/– Ube2e1+/– and Ube2e2+/+ Ube2e1+/+ control mice to diet-induced obesity." (PMID 39656538, 2024). "We next examined whether the Ube2e2–/– mice would recapitulate adiposity phenotypes, using the diet-induced obesity model." (PMID 39656538, 2024).
breast carcinoma (1 paper, 2024). "UBE2E2 has been shown to promote cancer cell movement and invasion in breast cancer cells through its action on ISG15." (PMID 39057719, 2024).
gestational diabetes mellitus (1 paper, 2025). "presented findings from a study that examined the association between variants of the UBE2E2 gene (polymorphism rs6780569) and the risk of gestational diabetes mellitus among Korean women." (PMID 40092641, 2025).
Parkinson’s (1 paper, 2014). "Genes showing similar co-expression patterns have been previously linked to Alzheimer’s (ANK1) and Parkinson’s disease (UBE2E2, PCMT1, HPRT1 and RIT2)." (PMID 25493648, 2014).
prostate carcinoma (1 paper, 2019). A carcinoma that arises from epithelial cells of the prostate gland. "Ubiquitin-conjugating enzyme E2 E2 (UBE2E2), and UBE2N were upregulated in prostate cancer and linked to hypoxia signaling." (PMID 30972102, 2019).
renal cell carcinoma (1 paper, 2019). "Module 2 included NEDD4, CDC27, UBE2E2, and TCEB1 associated with ubiquitin-mediated proteolysis and renal cell carcinoma pathways." (PMID 31178673, 2019).
cancer (4 papers, 2018 to 2024). A tumor composed of atypical neoplastic, often pleomorphic cells that invade other tissues. "The E2 enzyme UBCH8 (also known as UBE2E2) is currently less investigated in cancer." (PMID 36771004, 2023).
tumor (2 papers, 2023 to 2025). "Herein, our data demonstrate that UBE2E2 plays tumor-promoting roles in OvCa and suggest its potential use in a novel therapeutic strategy." (PMID 36765041, 2023). "Because EMT is an important cellular program in tumor migration, we thus verified the role played by UBE2E2 in EMT induction." (PMID 36765041, 2023). "Fluorescence imaging and average radiance values indicated that UBE2E2-depleted OvCa cells formed fewer tumor nodules than the control cells in orthotopic OvCa xenograft models and intraperitoneal xenograft models." (PMID 36765041, 2023).
metabolic disease (1 paper, 2024). A congenital disorder (due to inherited enzyme abnormality) or acquired (due to failure of a metabolically important organ) disorder resulting from an abnormal metabolic process. "In establishing functional relevance for the UBE2E2 locus to metabolic disease, this study also implicates all 3 of these mechanisms underpinning functional manifestations of noncoding variation." (PMID 39656538, 2024).
UBE2E2 also shares sentences with these, for which no sentence is quoted: hepatocellular adenoma (1 paper); mesothelioma (1); metabolic syndrome (1); non-small cell lung carcinoma (1); ovarian carcinoma (1); psoriasis (1).